MS4A1 (membrane spanning 4-domains A1)
Description:
B-lymphocyte-specific membrane protein that plays a role in the regulation of cellular calcium influx necessary for the development, differentiation, and activation of B-lymphocytes. Functions as a store-operated calcium (SOC) channel component promoting calcium influx after activation by the B-cell receptor/BCR.
Synonyms: CD20; B1; Bp35; FMC7; CVID5; LEU-16; S7
Tractability: Small molecule: a structure with a bound ligand is known. Antibody: an approved drug acts on it; UniProt places it where antibodies can reach, with high confidence; its Gene Ontology location is reachable by antibodies, with high confidence; UniProt predicts a signal peptide or a membrane-spanning region; the Human Protein Atlas places it where antibodies can reach. PROTAC: ubiquitination databases record sites on it; its protein half-life has been measured. Other modalities: an approved drug acts on it.
Target class: Other ion channel; Ion channel; Miscellaneous ion channel; CD20 Ca2+ channel family
Gene: Protein-coding gene on chromosome 11 (60,455,752 to 60,470,752, forward strand). Ensembl gene ENSG00000156738.
Subcellular location: Cell membrane
Subcellular location (Human Protein Atlas): Plasma membrane
Gene Ontology:
Molecular function: identical protein binding; immunoglobulin binding; MHC class II protein complex binding; protein binding; epidermal growth factor receptor binding
Biological process: B cell activation; B cell differentiation; B cell receptor signaling pathway; calcium ion import into cytosol; protein tetramerization; store-operated calcium entry; B cell proliferation; cell surface receptor signaling pathway; humoral immune response; positive regulation of calcium ion import across plasma membrane
Cellular component: cell surface; extracellular exosome; extracellular region; plasma membrane; plasma membrane raft; external side of plasma membrane; membrane
Genetic constraint (gnomAD): Loss-of-function variants: 16 observed, 24.55 expected, observed/expected ratio (o/e) 0.65, 90% interval 0.44 to 0.99. The upper end of that interval is the gene's LOEUF score, 0.99, which puts it in group 4 of 6, group 1 being the genes least tolerant of losing a copy. Missense variants: 341 observed, 363.07 expected, observed/expected ratio (o/e) 0.94, 90% interval 0.86 to 1.03. Synonymous variants: 126 observed, 121 expected, observed/expected ratio (o/e) 1.04, 90% interval 0.9 to 1.21.
Gene-disease validity (ClinGen):
ClinGen rates the evidence that MS4A1 causes each of these diseases.
immunodeficiency, common variable, 5 (autosomal recessive): Limited.
Homologues: Orthologues: chimpanzee MS4A1 (99% identical), macaque MS4A1 (97% identical), rabbit MS4A1 (80% identical), rat Ms4a1 (77% identical), guinea pig MS4A1 (74% identical), dog MS4A1 (74% identical), mouse Ms4a1 (73% identical), pig MS4A1 (73% identical), zebrafish ms4a17a.17 (21% identical), zebrafish ms4a17a.1 (20% identical), zebrafish si:ch73-56d11.3 (20% identical), zebrafish ms4a17a.11 (20% identical), and 19 more. Paralogues in human: MS4A8 (21% identical), MS4A14 (19% identical), MS4A15 (19% identical), MS4A12 (18% identical), MS4A4A (18% identical), MS4A18 (17% identical), MS4A7 (16% identical), MS4A5 (16% identical), MS4A6A (16% identical), MS4A10 (15% identical), MS4A2 (14% identical), MS4A3 (13% identical), and 4 more.
Diseases named in the same sentence as MS4A1 in open-access papers:
MS4A1 is named in the same sentence as 86 diseases in open-access papers, as found by Europe PMC text mining. Sharing a sentence is not in itself a finding about the gene and the disease. The quoted sentences say what the papers report.
lymphoma (17 papers, 2013 to 2024). A malignant (clonal) proliferation of B- lymphocytes or T- lymphocytes which involves the lymph nodes, bone marrow and/or extranodal sites. "Furthermore, cases with CD20-negatively converted lymphomas should be screened for the genomic loss of MS4A1." (PMID 28887496, 2017). "MS4A1 is a characteristic marker of B cells and is closely related to the treatment and prognosis of lymphomas and lymphocytic leukemias." (PMID 39717774, 2024). "Immunotherapies targeting the B-lymphocyte antigen CD20 (gene name: MS4A1, or Membrane Spanning 4-Domains A1) are currently the standard care for refractory or relapsing CD20-positive lymphomas." (PMID 33925941, 2021). "Recently, MS4A1 has also been detected in other cancer tissues, including glioblastoma, mucinous colorectal adenocarcinoma, lymphomas, esophageal cancer, ovarian cancer, glioma, and lung adenocarcinoma, indicating that the therapeutic application of Rituximab may extend beyond B-cell lymphomas." (PMID 39717774, 2024). "Of note, several genes reflecting B cells (CD20/MS4A1, CD19, CD22, CD79B) were significantly highly expressed in HLA‐I+ compared to HLA‐I− lymphomas, suggesting that the prognostically favorable B‐cell‐rich TME is a feature of HLA‐I+ HL." (PMID 38836098, 2024). "Next, we determined MS4A1 (CD20), CD74 and IL4R gene expression levels in 84 lymphoma samples across different tumor stages (stage I-III/IV) and compared to expression in 12 healthy tissue controls using quantitative PCR of tissue biopsies." (PMID 36353222, 2022). "MS4A1 (CD20) is an important marker of B cell differentiation and an important target for immunotherapy in lymphoma." (PMID 32850406, 2020). "The difference in the expression patterns of genes between the healthy and DLBCL samples in the canine dataset highlighted important lymphoma-specific up-regulated genes including DHFR, MS4A1, MYC, POLA1, POLE, RRM1, TOP2A and TYMS." (PMID 24023754, 2013). "In addition, new analysis predicted lymphoma subtypes using cell-of-origin markers that hematopathologists use in the clinical routine, including CD3, CD5, CD19, CD79A, MS4A1 (CD20), MME (CD10), BCL6, IRF4 (MUM-1), BCL2, SOX11, MNDA, and FCRL4 (IRTA1)." (PMID 38745770, 2024). "MS4A1 (CD20) is a critical marker of B-cell development and a therapeutic target in lymphoma." (PMID 36276869, 2022). "Indeed, gene markers known to be highly expressed by transitional and naïve B cells such as Membrane Spanning 4-Domains A1 (MS4A1), CD79B, and T-Cell Leukemia/Lymphoma 1A (TCL1A) were enriched in samples from ITx patients." (PMID 31134051, 2019).
melanoma (11 papers, 2016 to 2025). A malignant, usually aggressive tumor composed of atypical, neoplastic melanocytes. "In melanoma immune response prediction, we identified MS4A1 as a crucial hub gene, which is consistent with previous studies." (PMID 40917881, 2025). "Moreover, we also found that the high expression levels of CXCL13, FCRLA, MS4A1, and PLA2G2D were positively associated with the better response of melanoma patients treated with anti-PD1 and anti-CTLA4." (PMID 34395521, 2021). "In addition, expression levels of IGF1 and MS4A1 were correlated in stage IV (r = 0.5928 (p = 0.0199), Spearman’s rank correlation) melanomas." (PMID 28928360, 2017). "Four region-specific marker genes (PMEL for melanoma region, COL1A1 for stroma region, CXCL10 for lymphoid tissue 2, and MS4A1 for lymphoid tissue 1) were identified from the ST data to demonstrate the accuracy of imputed expression." (PMID 39402626, 2024). "Our results showed that the CXCL13, FCRLA, MS4A1, and PLA2G2D were positively correlated with the level of CTL infiltration in the melanoma patients treated with anti-PD-L1 or anti-CTLA4." (PMID 34395521, 2021). "In contrast, there is evidence for such a model in melanoma, based on the correlation of large hypermutating clonal IgG1 expansions and high IGHG1/MS4A1 ratio with survival (p = 0.006, HR = 0.7), and cytotoxic activity of tumor-specific IgG1 antibodies." (PMID 31665076, 2019). "In the melanoma dataset, STModule identifies similar components from the two samples, including cancer cells (I), transition areas (II), lymphoid tissue (III; CD74, CD52, MS4A1), immune activities (IV-VI), CAFs, and melanocytes (GAPDH)." (PMID 40033360, 2025). "For each expected cell type in each region, we selected its marker genes from existing literature, which included PMEL for malignant cells in melanoma regions, COL1A1 for fibroblast in stroma regions, MS4A1 for B cells and CD14 for macrophage in lymphoid tissues." (PMID 39402626, 2024).
colorectal cancer (9 papers, 2015 to 2025). A primary or metastatic malignant neoplasm that affects the colon or rectum. "The expression of MS4A1 was shown to be positively correlated with the survival of colorectal carcinoma, which was consistent with our result that MS4A1 was highly expressed in low-risk group." (PMID 36726580, 2023). "MS4A1, the gene encoding the B-cell surface marker CD20, is significantly downregulated in human colorectal cancer." (PMID 40786043, 2025). "MS4A1 expression was found to be positively correlated with the survival of colorectal cancer patients, and T cell subsets express MS4A1 in humans." (PMID 36645174, 2023). "The expression level of MS4A1 in colorectal cancer is positively correlated with patients’ prognosis." (PMID 37920207, 2023). "MS4A1, the gene encoding the B cell surface marker CD20, is significantly downregulated in human colorectal carcinoma." (PMID 33986754, 2021). "On the contrary, MS4A1 is downregulated in some tumors, like breast cancer and colorectal cancer." (PMID 41036204, 2025). "Additionally, the expression level of MS4A1 in colorectal cancer correlates positively with patient survival rates." (PMID 40786043, 2025). "Furthermore, MS4A1 expression level in colorectal carcinoma is positively correlated with patient survival." (PMID 40917881, 2025). "In a study of colorectal cancer, CD20 (MS4A1) expression was noted on PB and tumour T cells, respectively." (PMID 35951029, 2022).
breast carcinoma (8 papers, 2021 to 2025). "And MS4A1 expression is associated with better prognosis in breast cancer patients and can serve as an independent prognostic factor." (PMID 40917881, 2025). "In breast cancer patients with high MS4A1 expression, immune-related pathways are enriched, suggesting an active immune status." (PMID 40917881, 2025). "Patients with breast cancer who had low levels of expression of the genes CD19, CD79A, IFIT5, MS4A1, and TCL1A had shorter disease-free survival times." (PMID 37684436, 2023).
chronic lymphocytic leukemia (8 papers, 2013 to 2025). "The second, obinutuzumab (Gazyva®), an anti-MS4A1 (CD20) mAb with low fucose content, has been approved for treatment of chronic lymphocytic leukemia (CLL)." (PMID 28822103, 2018).
B-cell lymphoma (7 papers, 2016 to 2025). "MS4A1 is associated with apoptosis of B-cell lymphoma Ramos cells." (PMID 34367245, 2021). "Rituximab, a mAb against MS4A1, was approved for the treatment of relapsed B-cell lymphomas and relapsed non-Hodgkin’s lymphoma." (PMID 39717774, 2024). "Anti-MS4A1 therapy has achieved a promising results in non-Hodgkin’s B cell lymphoma." (PMID 36969247, 2023). "MS4A1 played a vital role in the apoptosis of B-cell lymphoma Ramos cells." (PMID 34395521, 2021).
diffuse large B-cell lymphoma (5 papers, 2017 to 2024). "CD19, MS4A1 (CD20), and CD22 are specific target antigens for diseases, such as relapsed/refractory large B-cell lymphoma, mantle cell lymphoma, and diffuse large B-cell lymphoma (DLBCL)." (PMID 34975912, 2021).
lung carcinoma (5 papers, 2012 to 2025). "The results showed PLK1, LDHA, FURIN, FSCN1, and RAB27B were up-regulated in lung cancer tissues, and MS4A1 was down-regulated in lung cancer tissues." (PMID 37604869, 2023). "Furthermore, we also found that PLK1, LDHA, FURIN, FSCN1, and RAB27B were increased in NSCLC cancerous cell lines compared with that in normal human bronchial epithelium cell line BEAS-2B, MS4A1 was down-regulated in lung cancer cells lines." (PMID 37604869, 2023). "Generally, our study identified two important prognostic mRNAs (MS4A1, MS4A2) that were significantly altered between high- and low-risk patients with lung cancer and developed a risk model independent of the clinical factors." (PMID 40053252, 2025). "In our independent test set of 12 primary lung SCC cases MS4A1 expression was only 1.7 fold higher in tumor tissue (lung SCC) compared with autologous normal lung, whereas CARD18 was 73 fold higher in tumor (ratio of lung cancer versus normal lung mean)." (PMID 22514692, 2012). "Moreover, MS4A1 is dysregulated in asbestos-related lung squamous carcinoma, RAB9B is a target of miR-15/16 which are highly related to lung cancer, LINC00539 is related to tumor immune response while long non-coding RNA, OGFRP1, regulates non-small-cell lung cancer progression." (PMID 33672117, 2021).
autoimmune disease (4 papers, 2022 to 2023). A disorder resulting from loss of function or tissue destruction of an organ or multiple organs, arising from humoral or cellular immune responses of the individual to their own tissue constituents. "The trans-acting lncRNA XR_001919671.1 of MS4A1 was gradually down-regulated with the growth and development of goat SMGs, which reduced the risk of autoimmune diseases in goat SMGs to some extent." (PMID 36672927, 2023). "B-cell-specific surface antigens MS4A1 and CD19 are used as targets in many autoimmune diseases, including MG, with MS4A1 surface molecule (aka CD20) being the most reliable marker of B lymphocytes and CD19 is expressed on a broader group of cells." (PMID 38140161, 2023). "Rituximab is also being used in other autoimmune diseases, including rheumatoid arthritis (RA), multiple sclerosis (MS), and neuromyelitis optica (NMO), showing the significance of targeting MS4A1 and B cells." (PMID 38140161, 2023). "IMGT/mAb-DB includes five mAbs targeting MS4A1 and two mAbs targeting CD19 for autoimmune diseases, of which four and one, respectively, have been approved by the FDA and/or EMA." (PMID 38140161, 2023). "Specific functions have been described for 3 members of the family (MS4A1/CD20; MS4A2; MS4A4A) and MS4A1/CD20 has proven to be an invaluable therapeutic target for the treatment of B cell malignancies and autoimmune diseases." (PMID 34346525, 2022).
lung adenocarcinoma (4 papers, 2018 to 2023). A carcinoma that arises from the lung and is characterized by the presence of malignant glandular epithelial cells. "Increased expression levels of BLK and MS4A1 have been reported in lung adenocarcinoma, and BLK and CD19 have been reported to be significantly correlated with the overall survival in patients with lung adenocarcinoma." (PMID 34943992, 2021). "In this research, samples of lung adenocarcinoma were interrogated with TME-related genes, among which high expression of PLK1, LDHA, FURIN, FSCN1, and RAB27B was correlated with poor OS, while high expression of MS4A1 was correlated with longer OS compared with the MS4A1 low expression." (PMID 37604869, 2023).
ovarian carcinoma (4 papers, 2021 to 2023). A malignant neoplasm originating from the surface ovarian epithelium. "Similarly, MS4A1 was positively related to prognosis and therapy response in ovarian cancer." (PMID 36157879, 2022). "In our study, we combined TMB and TIME evaluation methods to identify a set of genes related to the immune status of ovarian cancer, including CXCL13, FCRLA, MS4A1, and PLA2G2D." (PMID 34395521, 2021). "The results suggest that both peripheral blood markers and TICs can be used as prognostic predictors in patients with ovarian cancer, and CXCL9, CD79A, MS4A1, and MZB1 may be potential therapeutic targets for ovarian cancer immunotherapy." (PMID 36645174, 2023). "MS4A1 expression is positively correlated with CD4+ and CD8+T cell infiltration in ovarian cancer." (PMID 37762518, 2023).
colon cancer (3 papers, 2022 to 2025). "MS4A1 encodes the B cell surface marker CD20, is a member of the MS4A gene family which has been identified as n potential biomarker for predicting immunotherapy sensitivity in patients with colon cancer (CC) and having potential applications in gene therapy to inhibit CC progression." (PMID 40917881, 2025). "The MOD of MS4A1 and TNFRSF17 showed that the expression of MS4A1 and TNFRSF17 in the cell membrane of colon cancer was significantly lower than that of adjacent tissues (P<0.001)." (PMID 36203424, 2022).
autoimmune conditions (2 papers, 2019 to 2024). "Analogous to the use of anti-CD20 monoclonal antibodies like Rituximab in other autoimmune conditions, targeting MS4A1 could mitigate the excessive immune response characteristic of KD, thereby ameliorating coronary lesions and improving cardiovascular outcomes." (PMID 39239552, 2024).
cholangiocarcinoma (2 papers, 2020 to 2025). A carcinoma that arises from the intrahepatic biliary tree (intrahepatic cholangiocarcinoma) or from the junction, or adjacent to the junction, of the right and left hepatic ducts (hilar cholangiocarcinoma). "Additionally, immunohistochemical analysis of cholangiocarcinoma samples from our clinical study confirmed TLS positivity, characterized by MS4A1+follicular B cells surrounded by CD3+T cells." (PMID 39870490, 2025).
colitis (2 papers, 2008 to 2026). Inflammation of the colon. "Thus, TNBS colitis was characterized by an absence of significant changes in markers of T cells (Thy1, Tcrb, Tcrg, Zap70, Lck), B cells (Ptprc -B220-, Ms4a1 -Cd20-, Cd22, Cd79b) and NK cells (Baat, Ncam1 -Cd56-, B3gat1 -Cd57-)." (PMID 18928539, 2008).
colon adenocarcinoma (2 papers, 2020 to 2021). "The box diagram showed that MS4A1 was significantly highly expressed in LUAD, HNSC and kidney renal clear cell carcinoma, while in bladder carcinoma, colon adenocarcinoma, KICH, and READ tumours, MS4A1 was significantly lowly expressed." (PMID 34060213, 2021).
COVID-19 (2 papers, 2023). A disease caused by infection with severe acute respiratory syndrome coronavirus 2. "Especially a new population appeared in COVID-19 groups (Cluster 5), which highly expresses B cell-related genes, such as CD79A and MS4A1." (PMID 37446049, 2023). "To investigate if B cells from COVID-19 and HIV-1+ patients exhibited distinct transcriptional signatures, we performed integration and clustering on B cell and plasmablast populations (central and bottom clusters in UMAP), identified by upregulation of CD19/MS4A1 and CD38 respectively." (PMID 36992700, 2023).
Lung Squamous Cell Carcinoma (2 papers, 2012 to 2023). "MS4A1 dysregulation in asbestos-related lung squamous cell carcinoma is due to CD20 stromal lymphocyte expression." (PMID 37604869, 2023).
non-small cell lung carcinoma (2 papers, 2021 to 2025). A group of at least three distinct histological types of lung cancer, including non-small cell squamous cell carcinoma, adenocarcinoma, and large cell carcinoma. "For example, SCS was performed on patients with non-small cell lung cancer (NSCLC), which identified 12 key genes including MS4A1, CCL5, and GZMB as potential diagnostic and prognostic biomarkers." (PMID 41340965, 2025).
prostate carcinoma (2 papers, 2012 to 2023). A carcinoma that arises from epithelial cells of the prostate gland. "Ms4a1 was one of the most downregulated genes in the blood of male prostate cancer patients suffering from fatigue after radiation therapy." (PMID 36604457, 2023).
breast tumors (1 paper, 2025). "Changes in MS4A1 expression in breast tumors have been related to lower lipid metabolism and better survival." (PMID 40374694, 2025).
common variable immunodeficiency (1 paper, 2022). "For example, individuals with common variable immunodeficiency (CVID, for example, associated with deletions in CD19, MS4A1 (CD20) and CR2 (CD21) that impair B cell function) have been found to be at increased risk of severe disease and require further study." (PMID 34352148, 2022).
coronary artery aneurysms (1 paper, 2024). "Furthermore, the correlation between MS4A1 expression levels and disease severity underscores its potential as both a biomarker of disease activity and a prognostic indicator, providing insights into the severity of coronary artery aneurysms." (PMID 39239552, 2024).